HMGN3 (high mobility group nucleosomal binding domain 3)
Description:
Binds to nucleosomes, regulating chromatin structure and consequently, chromatin-dependent processes such as transcription, DNA replication and DNA repair. Affects both insulin and glucagon levels and modulates the expression of pancreatic genes involved in insulin secretion. Regulates the expression of the glucose transporter SLC2A2 by binding specifically to its promoter region and recruiting PDX1 and additional transcription factors. Regulates the expression of SLC6A9, a glycine transporter which regulates the glycine concentration in synaptic junctions in the central nervous system, by binding to its transcription start site. May play a role in ocular development and astrocyte function (By similarity).
Synonyms: TRIP7; PNAS-24; PNAS-25
Tractability: PROTAC: ubiquitination databases record sites on it.
Gene: Protein-coding gene on chromosome 6 (79,200,929 to 79,234,862, reverse strand). Ensembl gene ENSG00000118418.
Subcellular location: Nucleus
Subcellular location (Human Protein Atlas): Nucleoplasm; Cytosol
Gene Ontology:
Molecular function: protein binding; chromatin binding; nuclear thyroid hormone receptor binding; nucleosomal DNA binding
Biological process: chromatin organization
Cellular component: nucleoplasm; nucleus; chromatin
Genetic constraint (gnomAD): Loss-of-function variants: 2 observed, 9.47 expected, observed/expected ratio (o/e) 0.21, 90% interval 0.085 to 0.67. That is too few expected variants to judge how well the gene tolerates losing a copy. Missense variants: 59 observed, 70.21 expected, observed/expected ratio (o/e) 0.84, 90% interval 0.68 to 1.04. Synonymous variants: 29 observed, 22.32 expected, observed/expected ratio (o/e) 1.3, 90% interval 0.97 to 1.75.
Homologues: Orthologues: chimpanzee HMGN3 (100% identical), rabbit HMGN3 (94% identical), macaque HMGN3 (92% identical), dog HMGN3 (90% identical), guinea pig HMGN3 (88% identical), pig HMGN3 (87% identical), tropical clawed frog hmgn3 (75% identical), mouse Hmgn3 (66% identical), zebrafish hmgn6 (29% identical). Paralogues in human: HMGN2 (42% identical), HMGN4 (38% identical), HMGN1 (35% identical).
Diseases named in the same sentence as HMGN3 in open-access papers:
HMGN3 is named in the same sentence as 10 diseases in open-access papers, as found by Europe PMC text mining. Sharing a sentence is not in itself a finding about the gene and the disease. The quoted sentences say what the papers report.
liver cancer (2 papers, 2022 to 2024). An epithelial or non-epithelial malignant neoplasm that arises from the liver. "HMGN3 was only downregulated in MHCC-97H, while it was highly elevated in other liver cancer cells." (PMID 39591457, 2024).
Anxiety (1 paper, 2014). Intense feelings of nervousness, tension, or panic often arise in response to interpersonal stresses. "Therefore, asGEx remains constant in reciprocal hybrids and the tGEx seems likely to be regulated by epigenetic modifications in this model, making Hmgn3 a candidate gene of anxiety in a “gene × environment plasticity gene” construct in the HAB × LAB F1 intercross." (PMID 24672450, 2014). "The reported change in tGEx of Hmgn3 upon EE and UCMS further extends our documented plasticity genes of gene-environmental interactions in the regulation of anxiety-related traits." (PMID 24672450, 2014).
breast carcinoma (1 paper, 2017). "The HTR1B gene has been suggested to be involved in breast cancer progression and the HMGN3 gene has been published to be upregulated in breast cancer cell lines." (PMID 29262523, 2017).
gastric cancer (1 paper, 2024). A primary or metastatic malignant neoplasm involving the stomach. "High rates of expression of HMGB3, HMGN1, HMGN2, HMGN3, and HMGN4 are shown in gastric cancer." (PMID 39062899, 2024).
prostate carcinoma (1 paper, 2017). A carcinoma that arises from epithelial cells of the prostate gland. "HMGN3 is a regulator of a plethora of genes, some of which are involved in glucose and fat metabolism, including the putative tumor suppressor gene AZGP1, inactivation of which has been linked to tumor progression, poor prognosis, and increased cell proliferation in prostate cancer before." (PMID 29312579, 2017).
Sepsis (1 paper, 2022). Sepsis is defined as life-threatening organ dysfunction caused by a dysregulated host response to infection. "In this study, HMGN3 was down-regulated in patients, which laid the foundation for further verification of the role in sepsis." (PMID 35045818, 2022).
tumor (6 papers, 2008 to 2024). "We observed that HMGN1 were highly expressed in LUAD tissues compared with normal tissues at the RNA and protein level, while HMGN3/5 were expressed at a lower level in the tumor tissues compared to normal controls." (PMID 38710740, 2024). "Another example was HMGN3 which expressed isoform ENST00000620514 in 94% of tumor cells but 66% of normal cells." (PMID 37433798, 2023). "And promoter methylation of HMGN3/5 were up-regulated in tumor." (PMID 38710740, 2024). "Further, we detected several genes that were both mutated and differentially spliced in the same cell types, such as HMGN3 and UBE2G2 in tumor cells, CD74 and IFI30 in myeloid cells, and RPS2 in endothelial cells indicating their important roles in tumorigenicity." (PMID 37433798, 2023). "Of the forty entries, HMGN3 and TTK tyrosine kinase are candidates which could have tumor suppressor functions." (PMID 18397339, 2008). "We found that down regulation of each of 4 genes, i.e., SMAP1 (6q13), ZNF292 (6q14), HMGN3 (6q14), and UBE2J1 (6q15) significantly increased cell growth over background in colony formation assays performed in duplicate (P ≤ 0.0139), thus supporting a tumor suppressive role for these four genes." (PMID 29312579, 2017).
cancer (2 papers, 2020 to 2021). A tumor composed of atypical neoplastic, often pleomorphic cells that invade other tissues. "To date, only a handful of studies reported the association between HMGN3 and cancer." (PMID 34298646, 2021). "HMGN3 belongs to a family of chromatin remodeling proteins that are enriched in aggressive cancers and stem cells, due to their role in maintaining nuclear organization critical for stem cell properties, both during development and oncogenesis." (PMID 32471360, 2020).
neurodegenerative disease (1 paper, 2021). A disorder of the central nervous system characterized by gradual and progressive loss of neural tissue and neurologic function. "Further, it should be clarified whether alteration of mRNA levels HMGN3, NFY, their target genes are specific for HD or whether they are present in other neurodegenerative diseases." (PMID 34111223, 2021).
HMGN3 also shares sentences with these, for which no sentence is quoted: type 2 diabetes (1 paper).